MED11 (mediator complex subunit 11)
Description:
Component of the Mediator complex, a coactivator involved in the regulated transcription of nearly all RNA polymerase II-dependent genes. Mediator functions as a bridge to convey information from gene-specific regulatory proteins to the basal RNA polymerase II transcription machinery. Mediator is recruited to promoters by direct interactions with regulatory proteins and serves as a scaffold for the assembly of a functional pre-initiation complex with RNA polymerase II and the general transcription factors.
Synonyms: HSPC296; MGC88387; NDDRSB
Tractability: Small molecule: a structure with a bound ligand is known. PROTAC: ubiquitination databases record sites on it.
Gene: Protein-coding gene on chromosome 17 (4,731,428 to 4,733,608, forward strand). Ensembl gene ENSG00000161920.
Subcellular location: Nucleus
Subcellular location (Human Protein Atlas): Nuclear bodies; Nucleoplasm
Pathways (Reactome):
Developmental Biology: Transcriptional regulation of white adipocyte differentiation
Disease: RSV-host interactions
Metabolism: PPARA activates gene expression
Gene Ontology:
Molecular function: protein binding; transcription coregulator activity; ubiquitin protein ligase activity
Biological process: positive regulation of transcription elongation by RNA polymerase II; positive regulation of transcription initiation by RNA polymerase II; RNA polymerase II preinitiation complex assembly; protein ubiquitination; regulation of transcription by RNA polymerase II
Cellular component: core mediator complex; mediator complex; nucleus; nucleoplasm; ubiquitin ligase complex
Genetic constraint (gnomAD): Loss-of-function variants: 19 observed, 14.39 expected, observed/expected ratio (o/e) 1.32, 90% interval 0.92 to 1.84. The upper end of that interval is the gene's LOEUF score, 1.84, which puts it in group 6 of 6, group 1 being the genes least tolerant of losing a copy. Missense variants: 134 observed, 159.29 expected, observed/expected ratio (o/e) 0.84, 90% interval 0.73 to 0.97. Synonymous variants: 67 observed, 66.7 expected, observed/expected ratio (o/e) 1, 90% interval 0.82 to 1.23.
Homologues: Orthologues: chimpanzee MED11 (100% identical), guinea pig MED11 (98% identical), pig MED11 (98% identical), rat Med11 (98% identical), mouse Med11 (97% identical), macaque MED11 (94% identical), tropical clawed frog med11 (78% identical), zebrafish med11 (65% identical), dog MED11 (64% identical), Drosophila melanogaster MED11 (41% identical), Caenorhabditis elegans mdt-11 (25% identical).
Diseases named in the same sentence as MED11 in open-access papers:
MED11 is named in the same sentence as 7 diseases in open-access papers, as found by Europe PMC text mining. Sharing a sentence is not in itself a finding about the gene and the disease. The quoted sentences say what the papers report.
developmental delay (2 papers, 2025). "We also identified comphet variants in MED11 which are now leading diagnostic candidates in an undiagnosed patient experiencing neurodegeneration, developmental delay, brain abnormalities, chorea, and hypotonia." (PMID 40770127, 2025).
MED11 also shares sentences with these, for which no sentence is quoted: Intellectual disability (2 papers); Cerebral atrophy (1); Chorea (1); epilepsy (1); microcephaly (1); neurological disorders (1).